NMNAT2 (nicotinamide nucleotide adenylyltransferase 2)
Description:
Nicotinamide/nicotinate-nucleotide adenylyltransferase that acts as an axon maintenance factor (By similarity). Axon survival factor required for the maintenance of healthy axons: acts by delaying Wallerian axon degeneration, an evolutionarily conserved process that drives the loss of damaged axons (By similarity). Catalyzes the formation of NAD(+) from nicotinamide mononucleotide (NMN) and ATP. Can also use the deamidated form; nicotinic acid mononucleotide (NaMN) as substrate but with a lower efficiency. Cannot use triazofurin monophosphate (TrMP) as substrate. Also catalyzes the reverse reaction, i.e. the pyrophosphorolytic cleavage of NAD(+). For the pyrophosphorolytic activity prefers NAD(+), NADH and NaAD as substrates and degrades nicotinic acid adenine dinucleotide phosphate (NHD) less effectively. Fails to cleave phosphorylated dinucleotides NADP(+), NADPH and NaADP(+). Also acts as an activator of ADP-ribosylation by supporting the catalytic activity of PARP16 and promoting mono-ADP-ribosylation of ribosomes by PARP16. May be involved in the maintenance of axonal integrity (By similarity).
Synonyms: C1orf15; KIAA0479; PNAT2
Tractability: PROTAC: UniProt records ubiquitination sites on it; ubiquitination databases record sites on it.
Gene: Protein-coding gene on chromosome 1 (183,248,237 to 183,418,380, reverse strand). Ensembl gene ENSG00000157064.
Subcellular location: Golgi apparatus membrane; Cytoplasmic vesicle membrane; Cytoplasm; Cell projection, axon
Subcellular location (Human Protein Atlas): Cytosol
Pathways (Reactome):
Metabolism: Nicotinate metabolism
Gene Ontology:
Molecular function: nicotinamide-nucleotide adenylyltransferase activity; nicotinate-nucleotide adenylyltransferase activity; protein ADP-ribosyltransferase-substrate adaptor activity; catalytic activity
Biological process: negative regulation of cytoplasmic translation; axon development; NAD+ biosynthetic process via the salvage pathway; nucleotide biosynthetic process; 'de novo' NAD+ biosynthetic process from L-tryptophan; NAD+ biosynthetic process; NADP+ biosynthetic process
Cellular component: cytoplasm; cytosol; Golgi apparatus; Golgi membrane; cytoplasmic vesicle membrane; axon; extrinsic component of membrane; late endosome; synapse; trans-Golgi network; transport vesicle
Genetic constraint (gnomAD): Loss-of-function variants: 9 observed, 31.78 expected, observed/expected ratio (o/e) 0.28, 90% interval 0.17 to 0.49. The upper end of that interval is the gene's LOEUF score, 0.49, which puts it in group 2 of 6, group 1 being the genes least tolerant of losing a copy. Missense variants: 266 observed, 373.96 expected, observed/expected ratio (o/e) 0.71, 90% interval 0.64 to 0.79. Synonymous variants: 130 observed, 137.76 expected, observed/expected ratio (o/e) 0.94, 90% interval 0.82 to 1.09.
Homologues: Orthologues: chimpanzee NMNAT2 (100% identical), dog NMNAT2 (99% identical), macaque NMNAT2 (99% identical), guinea pig NMNAT2 (99% identical), pig NMNAT2 (99% identical), mouse Nmnat2 (99% identical), zebrafish nmnat2 (86% identical), tropical clawed frog nmnat2 (80% identical), rat Nmnat2 (79% identical), Drosophila melanogaster Nmnat (32% identical), Caenorhabditis elegans nmat-1 (27% identical), Caenorhabditis elegans nmat-2 (25% identical). Paralogues in human: NMNAT1 (35% identical), NMNAT3 (35% identical).
Diseases named in the same sentence as NMNAT2 in open-access papers:
NMNAT2 is named in the same sentence as 70 diseases in open-access papers, as found by Europe PMC text mining. Sharing a sentence is not in itself a finding about the gene and the disease. The quoted sentences say what the papers report.
glaucoma (14 papers, 2021 to 2026). Increased pressure in the eyeball due to obstruction of the outflow of aqueous humor. "This supports NMNAT2 loss (RNA and/or protein) in glaucoma as an important component of neurodegeneration and that individuals on the lower spectrum of NMNAT2 expression may be more susceptible to RGC loss." (PMID 39048544, 2024). "It is important to note, that these glaucoma eyes represent a more severe disease stage than might be first identified in the clinic and that this loss of NMNAT2 might be due to the loss of neuronal content in the retina." (PMID 36681854, 2023). "We have previously demonstrated that there is down-regulation of Nmnat2 in rodent RGCs in both an age- and disease-dependent manner and we hypothesized that NMNAT2 expression levels may be a potential risk factor in human glaucoma." (PMID 36681854, 2023). "Animal and cell culture data strongly implicate SARM1-dependent axon loss in some peripheral neuropathies, glaucoma, Parkinson disease, and other conditions, and human genetic studies support its involvement in rare axonopathies involving NMNAT2 mutation and in ALS." (PMID 35198877, 2022). "Several genes, such as NMNAT2 and TRIOBP, had robust associations with both phenotypes, with potential IOP-independent therapeutic translation for glaucoma." (PMID 41674619, 2026). "Recent research has demonstrated a significant reduction in NMNAT2 levels in mice afflicted with glaucoma or ocular hypertension." (PMID 39744428, 2025). "SARM1 becomes activated when the respective NMNAT is disrupted by mutation or (for NMNAT2) by axonal transport deficiency, underlying involvement of the pathway in LCA9 and glaucoma models respectively." (PMID 38538779, 2024). "Subsequent research further expanded on these findings and highlighted the importance of NMNATs and NAD homeostasis in maintaining retinal health, suggesting a potential involvement of reduced NMNAT2 activity in the pathogenesis of glaucoma." (PMID 38538779, 2024). "This pattern was also evident for NMNAT1 (n = 10 control eyes, 5 glaucoma eyes) and NMNAT2 (n = 8 control eyes, 5 glaucoma eyes)." (PMID 36681854, 2023). "Supporting these findings in rodent models of glaucoma, in human tissue, reduced NMNAT2 labelling has been demonstrated in enucleated eyes from glaucoma patients." (PMID 38983068, 2023). "NMNAT2, a key terminal enzyme in the salvage pathway, is predominantly expressed in retinal ganglion cell relevant layers of the retina and declines in glaucoma." (PMID 36681854, 2023). "Similarly, increasing NMNAT2 expression broadly provides neuroprotection across mouse models of tauopathy, familiar AD, and glaucoma." (PMID 37292715, 2023). "As such, both NMNAT1 and NMNAT2 may be valid treatment targets in the context of glaucoma and optic neuropathies." (PMID 36681854, 2023). "NMNAT2 expression was variable in the retina and optic nerve head, which could potentially contribute to the variability of glaucoma progression." (PMID 36681854, 2023). "A potential link may exist for glaucoma pathogenesis via axonal survival factors, such as nicotinamide mononucleotide adenylyltransferase 2 (NMNAT2) and stathmin 2 (STMN2)." (PMID 36012964, 2022). "Furthermore, increasing stress negatively impacts NMNAT2 expression, indicating that a decline in NMNAT2 may induce vulnerability to axon degeneration in glaucoma." (PMID 34198948, 2021). "It is possible MKK4/7 and/or JNK1/2/3 directly target NMNAT2 for degradation, ultimately triggering SARM1 activation and allowing axonal degeneration after glaucoma-relevant injury." (PMID 41397991, 2025). "A recent study showed reductions in Nampt, Nmnat1, and Nmnat2 in RGCs in glaucoma patients, implying that not only the NAD+ level but also the NAD salvage pathway can be reduced in glaucoma." (PMID 37754233, 2023). "NMNAT2 labelling was significantly reduced only in the central retina GCC in glaucomatous samples (n = 11 control eyes, 7 glaucoma eyes)." (PMID 36681854, 2023).
glaucoma (continued). "While NMNAT2 levels may decrease with age (potentially increasing vulnerability), recent clinical trials suggest NAM, another NAD+ precursor, is safe and effective for glaucoma, a neurodegenerative disease." (PMID 38921475, 2024).
tauopathy (13 papers, 2012 to 2025). Neurodegenerative disorders involving deposition of abnormal tau protein isoforms (tau proteins) in neurons and glial cells in the brain. "NMNAT2 alterations were also found in a mouse model of tauopathy expressing mis-sense mutation P301L, found in some frontotemporal dementia and parkinsonism linked to chromosome 17 (FTDP-17) cases." (PMID 29515354, 2018). "In contrast, in vitro studies have reported an upregulation of NMNAT2 mRNA following caffeine treatment, an effect that was also observed in vivo in a different neurodegenerative model, where caffeine restored NMNAT2 levels in rTg4510 tauopathy mice." (PMID 40931339, 2025). "The expression of NMNAT2 is downregulated in AD patients' brains, and caffeine (1,3,7‐trimethylxanthine) increases the expression of NMNAT2 in cortex of wild type, NMNAT2 heterozygous knockout, and rTg4510 tauopathy mice." (PMID 35730144, 2022). "In line with this notion, NMNAT2 overexpression was found to delay injury-induced axonal degeneration in zebrafish and to protect mice against tauopathy-induced neurodegeneration." (PMID 29515354, 2018). "A similar explanation was proposed for the neuroprotective effect of lentiviral expression of NMNAT1 or NMNAT2 in the hippocampus of a mouse model of tauopathy." (PMID 29175372, 2018). "Systemic injection of caffeine, one of the identified NMNAT2 positive modulators, restored NMNAT2 expression to control levels in the rTg4510 mouse model of tauopathy." (PMID 28266613, 2017). "NMNAT2 is highly expressed in the mammalian brain, and NMNAT2 mRNA levels are reduced in PD, HD, AD, and tauopathy patients." (PMID 28293166, 2017). "Caffeine, one identified NMNAT2 positive-modulator, when systemically administered restored NMNAT2 expression in rTg4510 tauopathy mice to normal levels." (PMID 28266613, 2017). "Our previous studies found that NMNAT2 was greatly reduced in the cortex of rTg4510 transgenic mice, a tauopathy model." (PMID 28266613, 2017). "Our previous studies showed that NMNAT2 overexpression in the hippocampi of rTg4510 mice, a tauopathy model, is sufficient to reduce p-hTau burden." (PMID 27254664, 2016). "In rTg4510 transgenic mice, a Frontotemporal Dementia and Parkinsonism-17 (FTDP-17) tauopathy model, NMNAT2 abundance declines prior to the onset of neurodegeneration or memory deficits." (PMID 27254664, 2016). "Is this chaperone activity required for NMNAT2 to reduce tauopathy and protect neurons against protein stress?" (PMID 27254664, 2016). "For example, a screen for modulators of NMNAT2 expression in cortical neurons identified caffeine as a positive modulator of Nmnat2, and short-term treatment with caffeine was able to restore NMNAT2 expression in the rTg4510 tauopathy mouse model." (PMID 37503611, 2023). "Recent studies show that decreased endogenous Nmnat2 expression and function may play a role in mouse models of Alzheimer's disease and tauopathy neurodegenerative diseases." (PMID 23082226, 2012). "Interestingly, it has recently been reported that the progression of Alzheimer's disease in the APPswe/PS1dE9 transgenic mouse model and in a mouse model of tauopathy correlates with a decrease in Nmnat2 expression." (PMID 23082226, 2012). "Indeed, NMNAT2 overexpression delays injury-induced axon degeneration both in vitro and in vivo and alleviates neurodegeneration in the P301L mouse model of tauopathy." (PMID 34707482, 2021). "Furthermore, elevating NMNAT2 levels in tauopathy model mice suppressed neurodegeneration." (PMID 28293166, 2017).
Alzheimer disease (9 papers, 2012 to 2024). A progressive, neurodegenerative disease characterized by loss of function and death of nerve cells in several areas of the brain leading to loss of cognitive function such as memory and language. "NMNAT2 expression is decreased in brains with Alzheimer's disease and has a highly variable expression in aged postmortem human brains." (PMID 36681854, 2023). "Similarly, NMNAT2 expression (RNA and protein) is highly variable in aged postmortem human brains, and further decreased in brains with Alzheimer’s disease where lower NMNAT2 is correlated with worse cognition." (PMID 39048544, 2024). "Moreover, top hub genes in this module were associated with the development of Alzheimer’s disease, including VSNL1, INA, CHN1, NMNAT2, and MAP7D2." (PMID 37284017, 2023). "NMNAT2 was downregulated in Alzheimer's disease and strongly correlated with EPB41L4A-AS1." (PMID 34758883, 2021). "Previous studies mainly focused on NMNAT2's role in neurodegenerative diseases (e.g., Alzheimer's disease), which demonstrated that NMNAT2 could prevent neuron and axon from apoptosis." (PMID 27218101, 2016). "In Alzheimer disease brains, NMNAT2 levels are less than 50% of control levels, and we propose that enhancing NMNAT2 function may provide an effective therapeutic intervention to reserve cognitive function." (PMID 27254664, 2016). "Given that NAD+ is widely acknowledged to play in mitochondrial respiration, we analyzed the NAD+ synthesis pathway genes and found that NMNAT2 was down-regulated DEG in aging and Alzheimer's disease." (PMID 34758883, 2021). "Moreover, NMNAT2 was highly correlated with EPB41L4A-AS1 both in aging and Alzheimer's disease." (PMID 34758883, 2021).
Parkinson disease (9 papers, 2017 to 2024). A progressive degenerative disorder of the central nervous system characterized by loss of dopamine producing neurons in the substantia nigra and the presence of Lewy bodies in the substantia nigra and locus coeruleus. "The mRNA levels of NMNAT2 are significantly reduced in the brains of AD, Parkinson's disease (PD), and Huntington's disease (HD) patients." (PMID 38282024, 2024). "It has been reported that NMNAT2 depletion was related to SARM1-dependent axon degeneration in Parkinson's disease and other axonal disorders." (PMID 34758883, 2021). "NMNAT2 mRNA levels are reduced in the brains of Alzheimer’s, Parkinson’s, and Huntington’s disease." (PMID 37292715, 2023). "NMNAT2 is significantly reduced in Alzheimer’s, Huntington’s, Parkinson’s diseases." (PMID 28266613, 2017). "The detected alterations were specific and significant as the expression levels of NMNAT1, NMNAT2 and sterile alpha and TIR motif containing 1 (SARM1) were not significantly different in Parkinson’s disease patients compared to controls." (PMID 35397003, 2022).
colorectal cancer (8 papers, 2016 to 2025). A primary or metastatic malignant neoplasm that affects the colon or rectum. "We also observed an increase in mRNA levels of NMNAT2, which is associated with higher tumor grade, stage, and metastasis in colorectal cancer." (PMID 40669753, 2025). "For example, upregulation of NMNAT2 was associated with the presence, depth and stage of colorectal cancer." (PMID 36778644, 2023). "NMNAT2 was shown to be a promising diagnostic and therapeutic target for colorectal cancer However the role of NMNAT2 in lung adenocarcinoma is unclear." (PMID 33392072, 2020). "Colorectal cancer tissues show elevated NMNAT2 expression levels compared to adjacent normal tissues, and the NMNAT2 expression was found to correlate with colorectal cancer TNM staging and invasiveness." (PMID 38396769, 2024). "Overexpression of Nmnat2 in colorectal cancer was reported to enhance cell death induced by tiazofurin, an analog of NAD." (PMID 30631755, 2018). "Since cancer cells harbor high demand for energy, it is interesting to know if NMNAT2 is upregulated in colorectal carcinoma tissues." (PMID 27218101, 2016). "Colorectal cancer cells with a low NMNAT2 expression have demonstrated resistance to tiazofurin, which could be reversed by overexpressing NMNAT2 in tiazofurin-resistant colorectal cancer cell lines." (PMID 38396769, 2024). "Recent studies have shown that NMNAT2 is involved in colorectal cancer progression." (PMID 33392072, 2020). "Interestingly, previous study has reported overexpression of NMNAT2 enhanced sensitivity of colorectal cancer cells to specific pro-drug and improved therapeutic efficacy." (PMID 31805718, 2019). "Nmnat2 enzymatically converts tiazofurin to thiazole-4-carboxamide adenine dinucleotide, a potent inhibitor of inosine 5'-monophosphate dehydrogenase, required for guanylate synthesis in colorectal cancers." (PMID 30631755, 2018).
neuropathy (8 papers, 2012 to 2025). A disorder affecting the nervous system that manifests with pain, tingling, numbness, and/or muscle weakness. "Altogether, these data demonstrate that Nmnat2V98M/R232Q mice had a motor axonal neuropathy, consistent with the chronic electrophysiological features of human patients with NMNAT2-associated neuropathy." (PMID 36287209, 2022). "Collectively, our data establish NMNAT2 variants as the genetic basis of a human neuropathy and demonstrate an unexpected role for SARM1 as a driver of neuroinflammation in the peripheral nervous system." (PMID 36287209, 2022). "Here, we examined 2 brothers with severe neuropathy associated with NMNAT2 mutations." (PMID 36287209, 2022). "In support, a SARM1-dependent increase in cADPR levels has been reported in sciatic nerves of 2-month-old mice harbouring the human NMNAT2 LOF mutations (Nmnat2V98M/R232Q), with SARM1 being required for the neuropathy phenotypes in these mice." (PMID 39352636, 2025). "Our data suggest that neuronal growth and axon extension are initially relatively normal but then, in the absence of Nmnat2, axon regression leads to a loss of muscular innervation, resulting in paralysis and a fatal embryonic neuropathy." (PMID 23082226, 2012). "Targeting the degradation of NMNAT2 might also be an alternative for neuropathy." (PMID 32347537, 2020). "More work is necessary to determine whether NMNAT2 levels or activity change over development in a manner that would differentially impact chemotherapy-induced changes in cell viability (measured in embryonic cultured cells) and chemotherapy-induced neuropathy (measured in adult mice)." (PMID 26808812, 2016). "However, in our sarmopathy model created using two hypomorphic Nmnat2 variants, we find that SARM1 is chronically activated leading to a slowly progressive neuropathy; thus, axon loss does not occur as an all-or-nothing event." (PMID 40496808, 2025). "This mirrors the permanent rescue and continued growth previously reported in Nmnat2 null axons in the absence of SARM1, suggesting complete efficacy in both toxic and inherited types of neuropathy." (PMID 34870595, 2021). "Additionally, studies propose that it may not be NMNAT2 and SARM1 proteins that are crucial targets; instead, it is suggested that downstream players in different pathways significantly participate in axon degeneration and subsequent neuropathy development." (PMID 38275737, 2024).